DAP3 (death associated protein 3)
Diseases named in the same sentence as DAP3 in open-access papers (continued):
Sharing a sentence is not in itself a finding about the gene and the disease.
cancer (continued). "How does DAP3 signalling interact with the other signallings such as Wnt, β-catenin, TRAIL signalling to present discrepant roles in cancers?" (PMID 38352299, 2023). "In this study, the effects of DAP3, GSDME, PLK1, and PPP2R5B knockdown on cancer cell growth were analyzed by DepMap, a cancer survival-dependent gene database." (PMID 37415742, 2023). "Depmap database was used to explore genome-wide knockout library screening data, and pan-cancer analysis of DAP3, PPP2R5B, PLK1, and GSDME genes on cancer cell growth." (PMID 37415742, 2023). "Here the authors show that DAP3 functions as an RBP splicing modulator via two mechanisms, and that its overexpression leads to mis-splicing events in cancers." (PMID 35379802, 2022). "The results showed that the knockdown or silencing of DAP3 and PLK1 genes could inhibit the growth of most HCC cells and many other cancer cells." (PMID 37415742, 2023). "We further identified the elevated expression of DAP3 in HCC and found that DAP3 may be involved in HCC progression by participating in multiple cancer-related pathways, including the cell cycle, DNA replication and Wnt signaling pathways." (PMID 36686684, 2022). "The DAP3 expression was negative for most of the NT samples (52 out of 61), poorly differentiated carcinomas (two out of four; not significant), FTC (five out of five), TUMP (three out of three) and FTA (eight out of eight)." (PMID 19536094, 2009). "In addition, HML-10(DAP3) RNA has been detected previously in various human cancer-derived cell lines but not in most healthy tissues." (PMID 27980690, 2016).
infection (2 papers, 2021 to 2025). The state of being infected such as from the introduction of a foreign agent such as serum, vaccine, antigenic substance or organism. "A previous report suggests that the amount of mtDNA controls DAP3 protein expression and that infection with human immunodeficiency virus 1, which is detected by RLR, decreases mtDNA." (PMID 33401559, 2021).
DAP3 also shares sentences with these, for which no sentence is quoted: acute lymphoblastic leukemia (1 paper); amyotrophic lateral sclerosis (1); Burkitt lymphoma (1); esophageal carcinoma (1); lactic acidosis (1); mitochondrial disease (1); ovarian insufficiency (1); stomach adenocarcinoma (1); stomach cancer (1); Stroke (1); thyroid cancer (1).